SLC19A1 (solute carrier family 19 member 1)
Diseases named in the same sentence as SLC19A1 in open-access papers (continued):
Sharing a sentence is not in itself a finding about the gene and the disease.
cancer (continued). "This study offers a comprehensive pan-cancer analysis of SLC19A1, identifying it as an unfavorable prognostic marker across multiple cancer types." (PMID 40149548, 2025). "Although a heterogeneous response profile was identified in different cancers, higher SLC19A1 expression predicted a poorer response to immunotherapies in several cancers." (PMID 40149548, 2025). "SLC19A1 was negatively correlated with the expression of most immune checkpoints in most cancers, except in KICH." (PMID 40149548, 2025). "Lastly, future studies should aim to conduct functional validation experiments to elucidate the specific biological roles of SLC19A1 in various cancer contexts." (PMID 40149548, 2025). "Specifically, we present the first comprehensive pan-cancer analysis of SLC19A1, leveraging transcriptomic, proteomic, and epigenomic datasets from 33 cancer types." (PMID 40149548, 2025). "Given the essential function of SLC19A1 in the anti-neoplastic effect of anti-folate compounds including pemetrexed and methotrexate, its potential role in other anti-cancer therapeutics was explored." (PMID 40149548, 2025). "In conclusion, our comprehensive pan-cancer analysis of SLC19A1 underscores its potential as a significant prognostic biomarker across various malignancies." (PMID 40149548, 2025). "The clinical status of these cancers was also analyzed, indicating that the mRNA of SLC19A1 is expressed differentially across different clinical stages in ACC, KICH, KIRC, PAAD, and OV." (PMID 40149548, 2025). "Based on the transcriptomic data of TCGA pan-cancer cohorts, the expression of RRP1B, RRP1, MAZ, DUS1L, and HGH1 was identified to correlate positively with the expression of SLC19A1 in 40 types of cancers." (PMID 40149548, 2025). "For an overview of the transcriptomic expression of SLC19A1 on a pan-cancer scale, the mRNA expression profile of TCGA pan-cancer cohorts was obtained and visualized." (PMID 40149548, 2025). "Considering the dysregulation of SLC19A1 at the transcriptomic and proteomic levels, the genetic alteration profile was summarized on a pan-cancer scale." (PMID 40149548, 2025). "The integration of multi-omics data, including transcriptomic, proteomic, and genomic analyses, provides a robust framework for understanding the diverse roles of SLC19A1 in cancer biology." (PMID 40149548, 2025). "Various deconvolution algorisms suggested SLC19A1 expression is negatively correlated with CD8-positive T cells in most of the cancers analyzed, except KICH, KIRC, KIRP, and THYM." (PMID 40149548, 2025). "These insights highlight the multifaceted roles of SLC19A1 in cancer biology and point to its potential as a therapeutic target." (PMID 40149548, 2025). "This study highlights the need for further exploration of SLC19A1 as a therapeutic target and its implications in cancer treatment strategies." (PMID 40149548, 2025). "The infiltration of B cells, T cells, NK cells, macrophages, etc., was assessed, and the correlation analysis with SLC19A1 expression suggested a lack of infiltrated anti-tumor immune cells is commonly seen in high SLC19A1 expression cancers." (PMID 40149548, 2025). "Recent evidence suggests that SLC19A1 is also responsible for the transport of cyclic dinucleotides, thus supporting the anti-cancer effect of its inhibition." (PMID 40149548, 2025). "The expression levels of TYMS, DHFR, and SLC19A1 were significantly higher in cancer ovarian samples than in normal ovarian samples." (PMID 39596024, 2024). "The identification of SLC19A1 as an importer of CDNs has implications for cancer immunotherapy and host-pathogen response." (PMID 37438132, 2023). "Folate is required for rapidly dividing cancer cells, and SLC19A1 has been exploited to mediate chemotherapeutic drug uptake." (PMID 37438132, 2023). "Solute carrier family 19 member 1(SLC19A1), as the first known transporter of cGAMP and other CDNs, has been suggested to exert influence on cancer immunotherapy." (PMID 35574387, 2022).
cancer (continued). "Taken together, these findings suggest that SLC19A1 plays crucial roles in PEM resistance of several cancer types." (PMID 29682186, 2018). "Some Class II genes that we found, such as SLC19A1 and ATAD3B, have been recently reported to associate with cancer outcomes." (PMID 28765560, 2017). "Therefore, the drug response of chemotherapies in different cancers and the SLC19A1 expression was obtained and compared." (PMID 40149548, 2025). "Given the pivotal function of cyclic dinucleotides in cancer and infection immunity, it was hypothesized that SLC19A1 could serve as a key molecule for the management of cancers." (PMID 40149548, 2025). "This demonstrated that SLC19A1 has a broad differential expression across these cancers." (PMID 40149548, 2025). "As multi-omics data support the prognostic value of SLC19A1, it was hypothesized SLC19A1 drives the downstream cascades to promote cancer progression." (PMID 40149548, 2025). "These SLC19A1-correlated genes in different cancers were therefore annotated." (PMID 40149548, 2025). "Cancer immunity and immune checkpoint expression largely affect tumor prognosis, suggesting that the effect of SLC19A1 on the prognosis of different tumors may be achieved through cancer immunity." (PMID 40149548, 2025). "Therefore, the importance of cyclic dinucleotides in anti-cancer and anti-infective immunity highlights the critical role of their intracellular transporter SLC19A1 in infection and cancer immunology." (PMID 40149548, 2025). "It was hypothesized that SLC19A1 plays a vital role in tumorigenicity and may serve as a potent breakthrough for the activation of innate immunity to kill cancer cells." (PMID 40149548, 2025). "Given the critical role of cyclic dinucleotide 2′3′-cGAMP in cancer immunity, SLC19A1 may serve as a potential target, as it has been shown to be the exchanger for both folate and 2′3′-cGAMP in mammalian cells." (PMID 40149548, 2025). "The SLC19A1 promoter status in these cancers all correlated positively with the CTLs." (PMID 40149548, 2025). "In OV and TCGT, cancer-associated fibroblasts and MDSC also correlated positively with SLC19A1." (PMID 40149548, 2025). "However, a previous study has demonstrated that cancer cells with low expression of SLC19A1 (solute carrier family 19 member 1) rely on SHMT1 rather than SHMT2 for 1C unit synthesis." (PMID 39286657, 2024). "For instance, though all three systems could facilitate the cellular uptake of antifolate drugs for cancer chemotherapy, SLC19A1 is the predominant route in many cancer cells." (PMID 36575193, 2022). "Therefore, the decreased expression of SLC19A1 is actually convenient for the survival of cancer cells, decreasing the uptake of PEM while maintaining the uptake of folate." (PMID 29682186, 2018). "Given the recent evidence that SLC19A1 serves as a cyclic dinucleotide transporter, the combination of therapeutics targeting SLC19A1 and cyclic dinucleotide analogs may be a novel direction for cancer treatment." (PMID 40149548, 2025). "However, the survival difference and mechanisms explored in this study all suggest that SLC19A1 could serve as a potential marker for cancer management and could also be used as a novel target for anti-cancer drug development." (PMID 40149548, 2025). "Considering pan-cancer characterization and multi-omics analysis can provide initial insights for potential mechanisms, multi-omics data were analyzed on a pan-cancer scale using algorithms including deconvolution to gain a comprehensive understanding of SLC19A1 in cancer biology." (PMID 40149548, 2025). "SLC19A1, a folate-organic phosphate antiporter, serves as the major transporter of cyclic dinucleotides, and its depletion and overexpression affect cyclic dinucleotide uptake and functional responses, which has implications for the immunotherapeutic treatment of cancer via cGAS-STING pathway." (PMID 33997099, 2021).
cancer (continued). "However, dysfunction of SLC19A1 could lead to resistance to anti-folate treatments in cancers." (PMID 40149548, 2025). "As shown in the heatmap, SLC19A1 was negatively correlated with most chemokines, receptors, and MHC in a pan-cancer context; however, SLC19A1 was broadly positively correlated with these cytokines in KICH and UVM." (PMID 40149548, 2025). "SLC19A1 is one of the most important transporters by which MTX is taken up by cells; its expression level therefore, can predict response to MTX therapy in cancer patients." (PMID 22546471, 2012). "Only four types of cancers showed no differential expression of SLC19A1 across the twenty-seven types of cancer studied." (PMID 40149548, 2025). "Given published evidence on transport of ThDP by cellular membrane transporters SLC19A1 and SLC44A4, this experimental design may overcome complex regulation of ThDP synthesis in cancer cells, being more straightforward to extend the interval of intracellular ThDP content." (PMID 33868388, 2021).
tumor (22 papers, 2011 to 2026). "First, while the correlations identified in this study are significant, the results rely on computational predictions, and the underlying mechanisms by which SLC19A1 influences tumor progression and immune modulation require further investigation." (PMID 40149548, 2025). "Regarding the infiltrated stroma cells and tumor purity, SLC19A1 was also widely associated with them in various tumors." (PMID 40149548, 2025). "In conclusion, the results of this multi-center prospective study suggest that rs2306283 (GA/AA) of SLCO1B1 in combination with rs1051266 (GG) of SLC19A1 are significantly associated with rapid tumor response to FOLFIRI/mCapeIRI in Chinese mCRC patients." (PMID 24143213, 2013). "Consistent with the transcriptomic data, genetic alteration of SLC19A1 also suggests an unfavorable prognosis and is associated with several neoplastic biomarkers, including TMB, MSI, neoantigen, HRD, ploidy, and tumor purity." (PMID 40149548, 2025). "SLC19A1 appears to play a crucial role in tumor progression by facilitating folate transport and influencing immune microenvironments." (PMID 40149548, 2025). "In BRCA, although tumor tissue partially expressed more SLC19A1, the single-CD68-positive cells indicated the majority of infiltrated immune cells were macrophages or monocytes instead of M2 macrophages." (PMID 40149548, 2025). "Immunofluorescence staining was performed to validate SLC19A1 expression in tumor tissues and its relationship M2 macrophages." (PMID 40149548, 2025). "These analyses address critical gaps in understanding how SLC19A1 orchestrates tumor progression and immune suppression, positioning it as a novel therapeutic target for precision oncology." (PMID 40149548, 2025). "Compared to the normal tissue, STAD was expressed relatively higher SLC19A1, while a higher infiltration of M2 macrophages was also found in the tumor tissue." (PMID 40149548, 2025). "Unlike previous studies, our work uniquely integrated genomic instability metrics, tumor stemness indices, and immune infiltration features to unravel the multifaceted roles of SLC19A1." (PMID 40149548, 2025). "Recently, cGAMP was identified as a soluble, extracellular immune transmitter derived from tumor cells and antigen-presenting cells, and SLC19A1 was identified as an importer of cGAMP for activation of STING in target cells." (PMID 38383773, 2024). "cGAMP can be derived from tumor cells via anti-folate transporter 1 (SLC19A1), which can activate the cGAS-STING pathway in cells." (PMID 35186921, 2022). "Inhibiting SHMT1 offers potential therapeutic options for tumor patients with low SLC19A1 expression." (PMID 35531073, 2022). "SLC19A1 was recognized to drive uptake of the new generation antifolate pemetrexed (PMX) into tumor cells." (PMID 35958555, 2022). "After LV injection, the expression of FPGS, GGH, MTHFD1L, and SLC19A1/RFC-1 was significantly higher in tumour tissue compared to the mucosa." (PMID 30269276, 2018). "A ratio between FOLR1 and SLC19A1 was calculated to identify the prominent uptake mechanism for each tumor subtype." (PMID 27064343, 2016). "High levels of SLC19A1 mRNA expression were significantly associated with MYCN amplification in both cohorts (Fisher's exact, P = 0.015 and P < 0.001 for the 42 and 650 tumor cohorts, respectively)." (PMID 25860940, 2015). "Elevated SLC19A1 expression may facilitate tumor progression by promoting folate-dependent nucleotide synthesis and supporting rapid cell proliferation." (PMID 41376620, 2025). "Inhibitors of SLC19A1 might synergize with existing therapies to counteract chemoresistance or enhance anti-tumor immunity by reducing M2 macrophage recruitment and restoring CD8+ T-cell activity." (PMID 40149548, 2025). "Inhibiting SHMT1 expression may be an emerging strategy for tumor patients with low SLC19A1 expression." (PMID 35531073, 2022).
tumor (continued). "In the future, SLC19A1 may be a marker for tumor patients that have an increased reliance on cytosolic 1C metabolic flux." (PMID 35531073, 2022). "SLC19A1 methylation correlated with tumor LINE1 methylation (r = 0.45, P = 0.02)." (PMID 24401732, 2014). "JJ assessed LINE1 methylation and SLC19A1 methylation of tumor samples." (PMID 24401732, 2014). "Median SLC19A1 methylation was 57.5% in post-decitabine tumor samples (range, 19-83%) (P = 0.63 in Wilcoxon signed rank test paired comparisons for 10 patients with both pre- and post-decitabine evaluable tumor samples)." (PMID 24401732, 2014). "The expression of SLC19A1 was also identified to be commonly correlated positively with HRD and tumor purity." (PMID 40149548, 2025). "In the folate cycle, SLC19A1 and MTHFD1 had upregulated expression in 6, 6 tumors and downregulated expression in 3, 1 tumor, respectively." (PMID 31828117, 2019). "The results of the study showed that tumour tissue of untreated patients had higher expression of FPGS, GGH, MTHFD1L, and SLC19A1/RFC-1 compared with mucosa, whereas expression of ABCC3/MRP3 and SLC46A1/PCFT was higher in mucosa compared with tumour." (PMID 30269276, 2018). "After LV injection, a significantly higher gene expression level of GGH, MTHFD1L, SLC19A1/RFC-1, and FPGS was seen in tumour tissue compared to mucosa." (PMID 30269276, 2018). "The ratio correlated significantly with tumor type (p<0.0001) and identified FOLR1 to mediate the uptake in TC to LCNEC with an inverted ratio in SCLC, where SLC19A1 seems to mediate the folic acid uptake." (PMID 27064343, 2016). "Furthermore, silencing SHMT1 with low SLC19A1 expression inhibits tumor growth by impairing pyrimidine biosynthesis in vitro and in vivo, whereas silencing SHMT1 with SLC19A1 overexpression cannot alleviate tumor growth." (PMID 35531073, 2022). "In non-tumor cells, cGAMP released by tumor cells may activate STING in neighboring immune cells within the tumor microenvironment via the SLC19A1 transporter or gap junctions." (PMID 36394642, 2023). "As SLC19A1 has previously been identified as a Myc target gene, there may also be a subset of non-amplified tumours with highly efficient methotrexate uptake." (PMID 25860940, 2015).
hematological malignancies (1 paper, 2018). "A single nucleotide polymorphism (SNP) of the SLC19A1 gene was reported to induce a difference in the transport and toxicity of methotrexate, an antifolate drug inhibiting DHFR, in patients with hematological malignancies." (PMID 29682186, 2018).
SLC19A1 also shares sentences with these, for which no sentence is quoted: melanoma (3 papers); Cognitive impairment (2); lymphoma (2); acute myeloid leukemia (1); Alzheimer disease (1); anencephaly (1); autism (1); autism spectrum disorder (1); Bladder Cancer (1); brain infarction (1); conotruncal heart defects (1); glioblastoma (1); infection (1); inflammatory bowel disease (1); intracranial aneurysm (1); ischemic stroke (1); leukopenia (1); metastatic melanoma (1); myelomeningocele (1); oral mucositis (1); ovarian carcinoma (1); pancreatitis (1); psychiatric disorder (1); Skin rash (1); systemic lupus erythematosus (1); toxic liver disease (1); urothelial carcinoma (1); uterine corpus endometrial carcinoma (1).